PPARA (peroxisome proliferator activated receptor alpha)
Diseases named in the same sentence as PPARA in open-access papers (continued):
Sharing a sentence is not in itself a finding about the gene and the disease.
atherosclerosis (continued). "Fenofibrate, a PPARα agonist, is an FDA-approved drug used in the treatment of hypertriglyceridemia, which is a major risk factor in the development of atherosclerosis." (PMID 40429862, 2025). "Research has found that exosomal miR-27b-3p from visceral fat can enter vascular endothelial cells, downregulating PPARα and activating the NF-κB pathway, increasing inflammation and atherosclerosis." (PMID 40520644, 2025). "According to them, the strong therapeutic effects of PPARα and PPARγ agonists benefit systemic lipid levels, glucose homeostasis, and atherosclerosis." (PMID 39062500, 2024). "Macrophage angiotensin-converting enzyme mitigates atherosclerosis by enhancing peroxisome proliferator-activated receptor alpha, thereby substantially altering lipid metabolism." (PMID 39364414, 2024). "We have already reported that ACE-overexpressed macrophages provided a protective function in atherosclerosis conditions by enhanced lipid metabolism represented by promoted β-oxidation and PPARα upregulation in the lesional macrophages." (PMID 37928535, 2023). "Intriguingly, lipin 1 has been demonstrated to be an activator of PPARα, suggesting that it constitutes a potential therapeutic target for atherosclerosis." (PMID 37964368, 2023). "Peroxisome proliferator-activated receptor-α (PPARα) has been of scientific interest for its potential role in atherosclerosis, due to its effects on HDL turnover." (PMID 36142760, 2022). "PPARα agonist GW7647 treatment of LDL receptor-null mice is shown to inhibit both atherosclerosis and the formation of macrophage foam cells in the peritoneal cavity." (PMID 36589809, 2022). "PPARα plays a crucial role in regulating multiple vascular pathological processes, including the lipid and glucose metabolism, vascular inflammation, and atherosclerosis." (PMID 36552585, 2022). "PPARα was demonstrated to regulate blood vessel growth in various diseases including cancer, atherosclerosis and ocular diseases." (PMID 36588740, 2022). "Based on these results, C. mas fruits showed protective effects against diet-induced hypertriglyceridemia and atherosclerosis across increased PPARα protein expression by regulating oxidative stress and inflammation." (PMID 35563963, 2022). "In humans, PPARα trans-repression occurs not only in the liver but also in isolated vascular endothelial cells, linking PPARα to systemic inflammation and atherosclerosis." (PMID 36589809, 2022). "Analysis of the impact of PPARα on atherosclerosis revealed that PPARα-KO on the ApoE-null background surprisingly reduced the number of atherosclerotic lesions, despite an increase in the circulating concentrations of atherogenic lipoproteins." (PMID 34360540, 2021). "The activation of PPARα is also considered to be beneficial to atherosclerosis, myocardial ischemia-reperfusion and hypertension." (PMID 33132907, 2020). "Agonists of PPARα demonstrated a preventive activity in atherosclerosis probably as a result of their impact on vascular inflammation, plaque instability and thrombosis." (PMID 31011554, 2019). "The regulation of energy metabolism, oxidative stress, and the inflammatory response by activation of PPARα is expected to lead to the prevention of atherosclerosis and CVDs." (PMID 31367355, 2019). "PPARα is another lipid-activated transcription factor and known to modulate lipid metabolism in the progression of atherosclerosis." (PMID 30008986, 2018). "In summary, preclinical data show that pemafibrate modulated gene expression mediated by PPARα, which in turn led to improved beneficial effects on atherogenic dyslipidaemia, inflammation and atherosclerosis, when compared with current PPARα agonists." (PMID 28978316, 2017).
atherosclerosis (continued). "As a result of its effects on the lipid metabolism and inflammation, PPARα can modulate physiopathological mechanisms implicated in NAFLD and atherosclerosis." (PMID 25875942, 2015). "Apart from its profound role in regulation of lipid metabolism, PPARα exerts anti-inflammatory and anti-atherogenic effects, which may be beneficial in the treatment of several metabolic diseases associated with inflammation such as non-alcoholic steatohepatitis and atherosclerosis." (PMID 25511156, 2014). "As a result of atherosclerosis progression, the contents of mRNAs for LXRα/β, PPARα/γ, and SREBP1 progressively rise." (PMID 23717417, 2013). "Because DKO mice, in contrast to single KO mice, are characterized by decreases in Pparα and Pparγ and accelerated atherosclerosis, we selected DKO mice to investigate the effect of fenofibrate and rosiglitazone." (PMID 23620818, 2013). "Treatment with a dual PPARα/γ agonist, compound 3q, notably increased atherosclerosis in control apoE knockout mice, while PPARγ and α agonists used alone in this model were protective." (PMID 23408783, 2013). "Previous research has demonstrated that the dual PPARα/γ agonist tesaglitazar reduces atherosclerosis in a mouse model of hyperlipidemia by reducing both lipid content and inflammation in the aorta." (PMID 23226761, 2012). "PPARA inhibits inflammatory reactions, one of the key factors involved in atherosclerosis, by stopping NFκB signalling, positively regulating IκBα, inhibiting JUN function, negatively regulating COX2, etc." (PMID 20937081, 2010). "In contrast, genetic deletion of PPARα in ApoE knockout mice resulted in more severe atherosclerosis." (PMID 19636418, 2009). "Conversely, overexpression of PPARα can reduce inflammation and prevent atherosclerosis." (PMID 40520644, 2025). "Notably, arachidonic acid acts as an activator of PPARα and has a therapeutic effect on atherosclerosis." (PMID 38699583, 2024). "From our score regressions, the atherosclerosis signaling pathway, IL-12 signaling and production in macrophages, PPARa/RXRa activation, MODY signaling, and complement system had the strongest associations with AUCs being 1.36-1.45 times the AUC of the clinical baseline model." (PMID 37308820, 2023). "In atherosclerosis, PPARα plays important roles in lipid homeostasis in different tissues." (PMID 36589809, 2022). "PPARα activation may indirectly influence atherosclerosis development through the effects of glucose and lipid homeostasis on adipose tissue, liver, and skeletal muscle." (PMID 35563963, 2022). "Several studies have reported the preventive effects of PPARα on inflammation and atherosclerosis." (PMID 35845076, 2022). "In the peripheral system, vortioxetine may have protective effects against atherosclerosis by influencing hepatic PPARα, like the fibrates." (PMID 34211395, 2021). "Despite this promising metabolic phenotype, the cell-type specific contributions of PPARα to atherosclerosis remain unclear." (PMID 34360540, 2021). "The PPARα may affects the initiation and progression of atherosclerosis by reducing inflammatory responses." (PMID 33201888, 2020). "The PPARα may affect the initiation and progression of atherosclerosis by reducing inflammatory responses." (PMID 33201888, 2020). "Furthermore, the atherosclerosis protective effects of PPARα activation are also thought to occur through enhancement of anti‐inflammatory response (Cao, Wen, & Li, 2014)." (PMID 31367355, 2019).
atherosclerosis (continued). "The distinct behavior of clade IV, which included two of the three liver specimens treated with carbon tetrachloride, did present distinctive enrichment of LXR/RXR activation and atherosclerosis signaling pathways, along with inferred activation of PPARA and KLF15." (PMID 29868123, 2018). "Moreover, pemafibrate (approved in Japan in July 2017) and LY518674 (phase II) are selective PPARα modulators used as anti-atherosclerosis agents in clinical trials." (PMID 29690611, 2018). "In addition, our study addresses the role of hepatic PPARα in the process of hepatic lipid reduction and alleviation of atherosclerosis after GTP treatment." (PMID 28777810, 2017). "Thus, the PPARs, particularly PPARα, play an important role in insulin sensitization, atherosclerosis, and metabolic diseases." (PMID 22570770, 2012). "The role of PPARα and PPARγ receptors in inflammation and atherosclerosis has been already described, and it is suggested, that PPARs activation regulates various targets that should decrease atherosclerosis, inflammation, and their complications." (PMID 22384120, 2012). "PPARα has the potential to affect atherosclerosis at two levels." (PMID 21382489, 2011). "Therefore, these properties of PPARα make it a possible target for therapy in rheumatoid arthritis (RA), which is characterized by accelerated atherosclerosis and impaired lipid profile." (PMID 21760804, 2011). "Since activated PPARα is a transcription factor affecting the expression of all genes containing PPREs (i.e., many hundreds of genes), it remains unclear which of the affected pathway(s) may be more relevant in human atherosclerosis." (PMID 37893070, 2023). "Among those, PPARα is a nutrient sensor, which allows for the adaptation to fatty acid catabolism, lipogenesis, and ketone body synthesis in response to feeding and starvation in rodent models during systemic inflammation, atherosclerosis, and non-alcoholic steatohepatitis (NASH)." (PMID 33505421, 2020). "Furthermore, these findings show a need to examine sulfatide metabolism in cardiomyocytes, endothelial cells, and vascular smooth cells to disclose any novel protective roles of PPARα in cardiovascular inflammation and atherosclerosis, particularly in relation to CST upregulation." (PMID 22645601, 2012). "Previous papers have revealed that a lipid-lowering synthetic ligand of peroxisome proliferator-activated receptor α (PPARα), fenofibrate, alleviates both atherosclerosis and a few nonlipid-associated autoimmune diseases such as autoimmune colitis and multiple sclerosis." (PMID 22792085, 2012). "Alternatively, PPARα could impact the inflammatory component of atherosclerosis." (PMID 21382489, 2011). "Similar to miR-21’s ability to downregulate PPARα in atherosclerosis, miR-BART20-3p directly binds the PPARα 3′-UTR to inhibit its expression." (PMID 40732023, 2025). "In rodent models of systemic inflammation, atherosclerosis, and non-alcoholic steatohepatitis (NASH), PPARα exerts negative regulation on pro-inflammatory and acute phase response signaling pathways." (PMID 39329770, 2024). "Genes MSR1, CCL2, and CXCL known to be involved in the development of atherosclerosis through the activation of LXR/RXR and PPARα were upregulated." (PMID 36831031, 2023). "Research has established that miR-21 induces a decrease in the expression of peroxisome proliferator-activated receptor alpha (PPAR-α) and an augmented hazard of atherosclerosis." (PMID 37736510, 2023). "However, some Dual PPARα/γ agonist such as compound 3q may accelerate atherosclerosis, it may related to the increase expression of the vascular endothelial activation and inflammation markers, such as P-selectin, MCP-1, VCAM-1, and CD36, that are also associated with plaque complexity." (PMID 35309069, 2022). "We have demonstrated the dueling relationship between PPARγ and PPARα in terms of macrophage differentiation, bacterial and viral clearance, IBD, and atherosclerosis." (PMID 35003101, 2021).
atherosclerosis (continued). "By contrast, Claudel andcolleagues demonstrated that treatment with the dual PPARα/γ compound,GW2331, for 11 weeks was more effective at attenuating atherosclerosis infemale apoE KO mice than rosiglitazone alone." (PMID 18288280, 2008). "Interestingly, PPARα has been demonstrated to negatively regulate both pro-inflammatory responses and APR, especially in the rodent models of NASH and atherosclerosis." (PMID 40806595, 2025). "In addition to activating PPARα signaling, many TCM prescriptions stimulate PPARγ–liver X receptor (LXR) α–ABCA1/ABCG1 signaling pathways, thereby ameliorating lipid profiles and atherosclerosis through upregulation of reverse cholesterol transport (RCT)." (PMID 38699583, 2024). "PPARα agonists such as clofibrate and gemfibrozil are therapeutic agents that have been shown to diminish serum TAG-rich lipoprotein levels, thus being critical to the treatment of atherosclerosis." (PMID 37964368, 2023). "A study analyzing the human arterial tissue proteomics identified several vascular and plasma biomarkers related to early atherosclerosis including TNF-α, insulin receptor, PPARα, and PPARγ protein networks, predictors of both development and site of atherosclerosis and CVD." (PMID 31354915, 2019). "We previously reported that ApoE-null mice lacking PPARα were resistant to diet-induced atherosclerosis, despite exhibiting the worsened lipid profile expected from the absence of PPARα." (PMID 24587793, 2014). "That the absence of PPARα also prevents L-NAME-induced atherosclerosis on the genetic background of ApoE-KO, reemphasizes the role of this gene in the development of atherosclerosis driven by several different triggers." (PMID 24587793, 2014). "The salient finding of the current study is that absence of PPARα gene prevents the aggravation of diet-induced atherosclerosis elicited by L-NAME in the ApoE-null mouse in vivo, independently of blood pressure or serum lipid alterations." (PMID 24587793, 2014). "The present study demonstrated that a combination of RSG and BEZ exerts a more efficient anti-inflammatory effect than RSG or BEZ alone, indicating that a combination of PPARα/γ agonists is capable of inhibiting the expression of MCP-1, thus delaying the process of atherosclerosis." (PMID 23408783, 2013). "However, our findings suggest that dual PPARα/γ agonist tesaglitazar inhibits the development of NAFLD and atherosclerosis in a diabetic mouse model by regulating glucose and lipid metabolism, and the inflammatory response." (PMID 23226761, 2012). "The role of PPARα in inflammation has been extensively studied in normal physiological processes (wound healing) and cardiovascular diseases (atherosclerosis); but the effect of PPARα mediated suppression of inflammation on tumors has not been characterized." (PMID 17327920, 2007). "Our results indicate that NAMPT knockdown exerts antiatherogenic effects by promoting macrophage RCT through the PPARα-LXRα pathway, and is consistent with the concept that NAMPT may be a negative regulator of macrophage RCT and the development of atherosclerosis in humans." (PMID 27229177, 2016). "Although by itself this reduction could not explain the protection from atherosclerosis, it suggested that PPARα could affect a system central to both atherogenesis and blood pressure regulation." (PMID 24587793, 2014).
atherosclerosis (continued). "We had previously reported that the attenuation of atherosclerosis in the DKO was accompanied by a sustained reduction in the aortic expression of MCP1, compared to that seen in the ApoE-null mice, and that this effect was dependent on the presence and the activation of PPARα." (PMID 24587793, 2014). "PPARα is also expressed in non-hepatic vascular cells, likely accounting for the effects of synthetic PPARα agonists on angiogenesis, endothelial permeability, and vascular adhesion capacity, which are important in the treatment of atherosclerosis." (PMID 25511156, 2014). "The likely beneficial effects of the higher expression of PPARA seen here for female liver include increases in HDL levels, decreases in triglycerides via increased beta-oxidation, induction of ABCA1, increases in insulin sensitivity, and protection from atherosclerosis." (PMID 21858147, 2011).